VIP (vasoactive intestinal peptide)
Diseases named in the same sentence as VIP in open-access papers (continued):
Sharing a sentence is not in itself a finding about the gene and the disease.
gastric ulcer (4 papers, 2014 to 2020). An ulcerated lesion in the mucosal surface of the stomach. "The serum levels of the inflammation-related cytokines motilin (MOT), somatostatin (SS), substance P (SP) and vasoactive intestinal peptide (VIP) were used to evaluate the preventive effects of insect tea against reserpine-induced gastric ulcers in ICR mice." (PMID 25187847, 2014). "It was additionally proven that intraperitoneal injection of VIP prevented stress-induced gastric ulcer formation by inhibiting mast cell degranulation and preventing lipid peroxidation." (PMID 24643520, 2014).
glioblastoma (4 papers, 2016 to 2024). The most malignant astrocytic tumor (WHO grade IV). "The involvement of VIP/PACAP-signalling has been recognised to have anti-tumour effects in glioblastoma cells." (PMID 34616669, 2021). "Pituitary adenylate cyclase-activating polypeptide (PACAP) and vasoactive intestinalpeptide (VIP) through the binding of vasoactive intestinal peptide receptors (VIPRs),perform a wide variety of effects in human cancers, including glioblastoma multiforme(GBM)." (PMID 27303300, 2016). "The VIP system regulates the proliferation of glioblastoma cells." (PMID 39063232, 2024). "Moreover, VIP blocks the invasion of glioblastoma cells (U-87MG) exposed to hypoxia by regulating HIF and epidermal growth factor receptor (EGFR) expression, which are involved in cell migration/invasion and angiogenesis." (PMID 39063232, 2024). "However, the VIP antagonist VIPhyb blocks the proliferation of U-87MG, U-118MG, and U-373MG glioblastoma cell lines through PAC1 receptors in in vivo and in vitro experiments." (PMID 39063232, 2024). "Stimulation of VIP/PACAP receptors triggers the cAMP/PKA axis, that reduces migration and invasion of glioblastoma cells via the inhibition of the PI3K/Akt and the Shh/GLI1 signalling routes." (PMID 34616669, 2021). "VIP, probably through VPC2 receptors, blocks the proliferation of T98G glioblastoma cells." (PMID 39063232, 2024).
glioma (4 papers, 2022 to 2025). A benign or malignant brain and spinal cord tumor that arises from glial cells (astrocytes, oligodendrocytes, ependymal cells). "VIP blocks the invasion of glioma cells exposed to hypoxia by regulating the expression of HIF and EGFR, which are involved in cell migration/invasion and angiogenesis." (PMID 39063232, 2024). "VIP/PACAP agonists reduce the invasion of glioma cells, whereas VIP antagonists increase the migration/invasion of tumor cells." (PMID 39063232, 2024). "VIP exerts an antiproliferative effect against serum-starved C6 glioma cells; however, in another study, VIP promoted the proliferation of the latter cells, which was blocked by VIP antagonists." (PMID 39063232, 2024). "Unlike previous peptides that exclusively exert antiproliferative action or a proliferative effect on glioma cells, GH-RH, oxytocin, and VIP promote both oncogenic and anticancer effects on these cells." (PMID 39063232, 2024). "VIP agonists decrease the invasion of C6/U-87MG glioma cells, whereas VIP antagonists augment the migration and invasion of tumor cells." (PMID 39063232, 2024). "VIP reduces the migration/invasion of glioma cells via protein kinase A-dependent inhibition of the Sonic Hedgehog/GLl1 and PI3K/Akt signaling pathways." (PMID 39063232, 2024). "VIP antagonists (e.g., VIPhyb) block the proliferation of glioma cells." (PMID 39063232, 2024). "Thus, VIP exerts proliferative and antiproliferative effects on glioma cells." (PMID 39063232, 2024). "PACAP and vasoactive intestinal peptide (VIP) modulate cyclic-AMP signalling and proliferation in C6 and T98G glioma models, revealing cell-context–dependent pro- and anti-growth actions." (PMID 40740778, 2025). "Under normal culture conditions, VIP and PACAP induce the proliferation of rat GBM-derived C6 glioma cells, while under serum-starved conditions, VIP and PACAP possess antiproliferative properties." (PMID 35456975, 2022).
graft versus host disease (4 papers, 2013 to 2023). An immune system disorder that occurs after allogeneic hematopoietic stem cell transplant and is a reaction of donor immune cells against host tissues. "We recently noted that VIP produced by activated T cells limits their proliferation in vitro, and VIP produced by donor plasmacytoid dendritic cells (pDCs) limits Graft-versus-Host Disease (GVHD) in vivo." (PMID 37153607, 2023). "For instance, vasoactive intestinal peptide (VIP) has been demonstrated to generate CD4+CD25+ regulatory T cells in vivo and inhibit graft-versus-host disease in an animal model." (PMID 33176790, 2020). "But VIP can act directly on the Teff cells – culture of CD25−Foxp3− Teff with VIP induces their differentiation into CD25+Foxp3+ Treg that express high levels of IL-10 and CTLA4 and are protective in a mouse model of graft versus host disease (GVHD)." (PMID 24550907, 2014).
heart failure (4 papers, 2013 to 2022). Inability of the heart to pump blood at an adequate rate to meet tissue metabolic requirements. "NFAT expression inducing cardiac fetal gene expression would explain the profound RV hypertrophy and risk for heart failure in VIP−/− mice." (PMID 23700405, 2013). "VIP (vasoactive intestinal peptide), cardioprotective in heart failure, and SMAD5, which has anti-apoptotic actions in cardiac myocytes were upregulated." (PMID 29556499, 2018). "Nevertheless, overexpression of cardiomyopathy genes in VIP−/− mice supports the concept of VIP's potential role in therapy for heart failure." (PMID 23700405, 2013). "In the current study, we examined if VIP knockout mice (VIP−/−) develop both right (RV) and left ventricular (LV) cardiomyopathy, manifested by LV dilatation and systolic dysfunction, as well as overexpression of genes conducive to heart failure." (PMID 23700405, 2013).
Hypercalcemia (4 papers, 2014 to 2025). An abnormally increased calcium concentration in the blood. "Nonneurologic paraneoplastic syndromes include secretory diarrhea from vasoactive intestinal peptide (VIP) secretion, Cushing's syndrome, hypercalcemia, and the syndrome of inappropriate antidiuretic hormone (SIADH)." (PMID 25328733, 2014).
lung disease (4 papers, 2011 to 2025). "A deficiency of VIP in the respiratory system is considered to be a pathogenetic factor in pulmonary disease." (PMID 21477377, 2011). "In the context of lung disease, vasoactive intestinal peptide (VIP), released by pulmonary sensory neurons following IL-5 stimulation, fosters allergic inflammation by acting on CD4+ T cells and innate lymphoid type 2 cells (ILC2s)." (PMID 39229121, 2025). "Inhaled liposomal vasoactive intestinal peptide (VIP) is an example of an LNP-packaged peptide drug targeted towards pulmonary disease treatment." (PMID 36140280, 2022). "This article reviews the physiological significance of VIP in cardiopulmonary system and the therapeutic potential of VIP-based agents in the treatment of pulmonary diseases." (PMID 21477377, 2011).
peripheral nerve injuries (4 papers, 2015 to 2023). "Despite the lack of VIP studies in SCI, there are some studies in models of peripheral nerve injuries that demonstrate how VIP is also able to promote remyelination and attenuate the inflammatory burden within the distal nerve stump following a nerve injury." (PMID 37646964, 2023). "Vasoactive Intestinal Peptide and PACAP are regeneration-associated neuropeptides that are up-regulated in motor, sensory, and sympathetic neurons following peripheral nerve injury." (PMID 31920495, 2019). "In the early stage of peripheral nerve injury, VIP and PACAP could balance pro-inflammatory cytokine production and prevent unnecessary macrophage recruitment." (PMID 31920495, 2019). "Vasoactive intestinal peptide (VIP) and pituitary adenylate cyclase-activating polypeptide (PACAP) are related neuropeptides most commonly upregulated by neurons, including nociceptors, following peripheral nerve injury." (PMID 37006298, 2023).
rheumatic diseases (4 papers, 2014 to 2021). "Recent studies also associate VIP levels to the progression of rheumatic diseases." (PMID 31861827, 2019). "Our results support the anti-inflammatory and anti-catabolic properties of VIP in rheumatic diseases and provide potential new targets for OA treatment." (PMID 34208590, 2021). "It is also important to note that sympathetic nervous system fibers innervate the joints, which explains the role of VIP in rheumatic diseases." (PMID 31861827, 2019). "In agreement with data reported in several rheumatic diseases, they found that serum VIP levels are lower in UC patients than in healthy controls." (PMID 31861827, 2019). "Moreover, since DCN, CTSB and MMP2 also promote the inflammatory process in OA, reduction mediated by VIP again corroborates its well-known anti-inflammatory role in rheumatic diseases." (PMID 34208590, 2021). "In addition, our results support the anti-inflammatory and anti-catabolic properties of VIP in rheumatic diseases." (PMID 34208590, 2021). "The effects of VIP reported in rheumatic diseases could be mediated in part by its action on the SF, as has been described in several in vitro studies." (PMID 31861827, 2019). "However, growing evidence supports the ability of VIP to regulate the intensity of the inflammatory process and the immune response that contribute to the pathogenesis of rheumatic diseases." (PMID 24409325, 2014).
temporal lobe epilepsy (4 papers, 2015 to 2022). A localization-related (focal) form of epilepsy characterized by recurrent seizures that arise from foci within the temporal lobe, most commonly from its mesial aspect. "Stereological quantification of VIP/CR cells in a model of temporal lobe epilepsy demonstrated that they survive in epileptic mice, despite a reduction in their somatostatin-expressing (Som) cell targets." (PMID 34819310, 2021). "VIP-expressing interneurons are among the populations that survive in patients with temporal lobe epilepsy; however, the VIP/CR population undergoes some of the largest transcriptomic changes among interneurons." (PMID 34819310, 2021). "Indeed, in human temporal lobe epilepsy brains, the receptors for the VIP peptide are increased in expression in the focus of the seizure." (PMID 35221922, 2022). "In the animal model of temporal lobe epilepsy, although there is a severe reduction of particular types of neurons, the number of VIP-expressing neurons seems not to be affected." (PMID 35221922, 2022).
amblyopia (3 papers, 2019 to 2020). Decreased vision that results from abnormal visual development. "During the sensitive period of visual development, amblyopia and a decrease in VIP expression in the LGBd were caused by the unequal input of binocular visual information, and this decrease in VIP expression promoted the development of amblyopia." (PMID 31429729, 2019). "This includes recovery from amblyopia induced during the critical period, an outcome replicated by optogenetic activation of VIP+ interneurons." (PMID 31481397, 2019). "The average optical density of positive cells in the VIP intervention group was higher than that in the Sefsol intervention group (P = 0.037) and amblyopia non-intervention group (P = 0.007) but lower than that in the normal control group (P = 0.000)." (PMID 31429729, 2019). "The average optical density of VIP-positive cells in the VIP intervention group was higher than that in the Sefsol intervention group (P = 0.015) and amblyopia non-intervention group (P = 0.055), but weaker than that in the normal group (P = 0.000)." (PMID 31429729, 2019). "At 9 weeks of age, the VIP intervention group had more VIP-positive cells than the Sefsol intervention group (P = 0.008) and the amblyopia non-intervention group (P = 0.017) but fewer than the normal group (P = 0.000)." (PMID 31429729, 2019). "Specifically, amblyopia resulted in increased numbers of active SOM+ interneurons, without any detectable effect on either VIP+ or PARVA+ cells." (PMID 32728106, 2020).
amyloidosis (3 papers, 2012 to 2024). A disorder characterized by the localized or diffuse accumulation of amyloid protein in various anatomic sites. "A recent study revealed that shining light flickering gamma at 40 Hz activate the VIP peptide to drive the glymphatic system for better amyloid clearance, which contributes to improving AD physiology." (PMID 39246604, 2024). "Constitutive overexpression of VIP in the hippocampus reduces inflammation and attenuates amyloidosis in transgenic PS1/APP mice, which present increased β-amyloid production associated with behavioral abnormalities." (PMID 32765225, 2020). "Interestingly, both immunosuppressive and anti-amyloidosis effects of VIP have been confirmed in vivo." (PMID 32765225, 2020). "Furthermore, constitutive overexpression of VIP in the hippocampus reduced inflammation and attenuated amyloidosis in a transgenic mouse model of AD." (PMID 22328918, 2012).
atrial fibrillation (3 papers, 2021 to 2025). A disorder characterized by an electrocardiographic finding of a supraventricular arrhythmia characterized by the replacement of consistent P waves by rapid oscillations or fibrillatory waves that vary in size, shape and timing and are accompanied by an irregular ventricular response. "In this study, integrative bioinformatics analysis revealed that infarct-mediated overexpression of potential miR-662/CREB1 pathway-induced neuropeptide VIP may be associated with the risk of atrial fibrillation." (PMID 34853624, 2021).
autism spectrum disorder (3 papers, 2022 to 2026). A spectrum of developmental disorders that includes autism, and Asperger syndrome. "Furthermore, increased VIP and VIP receptor 2 (VPAC2) levels in newborns are associated with an increased chance of developing autism spectrum disorder (ASD), further supporting the role of VIP in neurodevelopment." (PMID 35203552, 2022).
autoimmune thyroiditis (3 papers, 2018 to 2020). "Given that a decreased expression of VIP has been reported in several autoimmune and inflammatory diseases, we first evaluated serum levels of VIP in GD and HT patients, in an attempt to explore its relevance in two clinically opposed thyroid autoimmune diseases." (PMID 32747757, 2020).
bladder cancer (3 papers, 2017 to 2022). "Vasoactive intestinal peptide KO mice have enhanced susceptibility to death from MB49 bladder cancer injected in the hind leg." (PMID 28824540, 2017). "In this second study the investigators used PGP 9.5 to visualize nerve fibers in the tumor stroma as well as to demonstrate neuronal reactivity to vasoactive intestinal peptide (VIP), confirming innervation of the bladder carcinoma." (PMID 35454883, 2022). "In this study, VIP KO mice have a higher mortality rate with exposure to MB49 bladder cancer cell line than C57BL/6 mice, supporting the concept that VIP inhibits the susceptibility to death from bladder cancer." (PMID 28824540, 2017). "We found that administration of VIP to bladder cancer cells cultured in vitro led to decreased cell growth, suggesting that the presence of VIP plays a role in regulating bladder cancer cell proliferation, at least in part through VPAC1 receptor." (PMID 28824540, 2017). "Further studies into the mechanism of VIP’s action on bladder cancer are nonetheless warranted to understand the full benefit of in vivo VIP administration as well as any potential side effects related to dosage." (PMID 28824540, 2017). "The Kaplan–Meier plot shows statistically significantly (p = 0.002) increased mortality among VIP KO mice injected with MB49 bladder cancer, whereas all other mice (VIP KO controls, WT controls, and WT mice injected with cancer) survived until the end of term." (PMID 28824540, 2017). "A potential novel therapeutic agent for bladder cancer is vasoactive intestinal peptide (VIP), which is a 28-amino acid peptide that has multiple therapeutic actions, including bronchodilatory and anti-inflammatory properties." (PMID 28824540, 2017). "The finding that VIP receptors are present in bladder carcinomas lends support to the concept that we may plausibly treat bladder cancer with VIP." (PMID 28824540, 2017). "With the recent availability of VIP knockout (VIP KO) mice, we hypothesized that these animals have enhanced mortality to bladder cancer." (PMID 28824540, 2017). "Additionally, other studies have shown that PAC1, VPAC1, and VPAC2 receptor transcripts were expressed in the urothelium and detrusor smooth muscle of mouse urinary bladder, which suggests VIP’s potential role in regulating bladder cancer cell growth." (PMID 28824540, 2017). "In vitro studies indicated that the presence VIP in high doses reduced MB49 cell growth, as well as macrophage inhibitory factor (MIF), a growth factor in bladder cancer cells." (PMID 28824540, 2017). "We hypothesized that VIP would decrease cell growth by decreasing the activity of macrophage inhibitory factor (MIF), a known growth factor in bladder cancer cells." (PMID 28824540, 2017). "Vasoactive intestinal peptide, which currently does not have a therapeutic indication, may potentially be a novel medicine to treat bladder cancer." (PMID 28824540, 2017). "Compared to cells grown in the absence of VIP, those grown in the presence of VIP also showed decreased extracellular MIF accumulation, a molecule known to promote proliferation of bladder cancer cells." (PMID 28824540, 2017).
cardiomyopathy (3 papers, 2013 to 2022). A disease of the heart muscle or myocardium proper. "Our study is the first to test the effect of loss of the VIP gene on striated left and right ventricular muscle and function, supporting the role for VIP as potential therapeutic option in cardiomyopathy." (PMID 23700405, 2013). "Lungs from VIP−/− mice showed overexpression of cardiomyopathy genes: Myh1 was upregulated 224 times over WT, and Mylpf was increased 72 fold." (PMID 23700405, 2013). "The significance of bilateral cardiomyopathy in VIP−/− mice is that this links the VIP gene to critical whole heart myosin gene overexpression, tied to abnormal function in its absence, and supports the concept of VIP therapy for cardiac disease." (PMID 23700405, 2013).
demyelinating disease (3 papers, 2022 to 2024). A broad group of disorders that affect the myelin sheaths that cover the neurons. "Altogether, the evidence presented here supports the hypothesis that both PACAP and VIP are potential inducers of microglial phagocytosis and could aid in stimulating the removal of myelin debris in demyelinating diseases such as MS." (PMID 35563181, 2022).
diabetic neuropathy (3 papers, 2017 to 2024). A chronic, pathological complication associated with diabetes mellitus, where nerve damages are incurred due to diabetic microvascular injury involving small blood vessels that supply these nerves, resulting in peripheral and/or autonomic nerve dysfunction. "In the intestinal mucosa of W-GSH animals, an overexpression of VIP-IR varicosities was detected, and in a previous work of our group, an increased cell body of VIP-IR submucosal neurons was demonstrated in animals treated with l-glutathione in a model of diabetic neuropathy." (PMID 38607556, 2024). "These adaptive changes in the proportion of VIP+ and nNOS+ neurons with no modifications in SP-containing nerves appear to be phenotypic characteristics of ENS resembling those found in diabetic neuropathy." (PMID 28642706, 2017).
ganglioneuroma (3 papers, 2018 to 2024). A benign neuroblastic tumor of the sympathetic nervous system that occurs in childhood. "It is rare in VIP-secreting neuroblastic tumors since this peptide is generally associated with differentiated tumors (ganglioneuroma) or tumors undergoing differentiation (ganglioneuroblastoma)." (PMID 39328672, 2024). "Literature suggests that VIP production usually derives from more differentiated neural crest tumors, such as ganglioneuromas and ganglioneuroblastomas." (PMID 39328672, 2024).